RNU6-685P (RNA, U6 small nuclear 685, pseudogene)
Gene: Small nuclear RNA gene on chromosome 2 (82,268,612 to 82,268,706, forward strand). Ensembl gene ENSG00000252897.
Homologues: Orthologues: chimpanzee U6 (100% identical), dog U6 (80% identical). Paralogues in human: RNU6-63P (93% identical), RNU6-144P (89% identical), RNU6-140P (88% identical), RNU6-536P (88% identical), RNU6-820P (88% identical), RNU6-1158P (87% identical), RNU6-20P (87% identical), RNU6-211P (87% identical), RNU6-22P (87% identical), RNU6-35P (87% identical), RNU6-637P (87% identical), RNU6-961P (87% identical), and 1288 more.